IL33 (interleukin 33)
Diseases named in the same sentence as IL33 in open-access papers (continued):
Sharing a sentence is not in itself a finding about the gene and the disease.
tumor (continued). "Although the difference was small, most likely because IL-33 enhances P29 cell death only in nutrient-starved and hypoxic regions in tumours, these results indicate the physiological role of IL-33 in tumour growth." (PMID 26775708, 2016). "To further validate the pericytes and stromal cells as the major source of IL-33 production in in vivo tumours, we isolated different cell types from the tumour microenvironment." (PMID 27150562, 2016). "Taken together, these findings demonstrate that pericytes and tumour stromal cells are the primary source of IL-33 in the tumour microenvironment." (PMID 27150562, 2016). "The results showed that a higher amount of IL-33 protein was present in P29 tumours than in A11 tumours, which exhibited rather low levels compared with that in the lung." (PMID 26775708, 2016). "In NSCLC patients, expression of IL33 and IL1RL1 was found to be increased in tumor tissue compared to adjacent non-tumor tissue, and this expression was associated with disease clinical stage." (PMID 28119694, 2016). "We found that P29 tumours tended to show a faster growth rate in IL-33−/− mice than in B6 mice, whereas A11 tumours grew at comparable rates." (PMID 26775708, 2016). "It revealed that serum IL-31 was related to tumor stages (P = 0.024) and serum IL-33 was close to the disease process: tumor stages (P = 0.035), depth of invasion (P = 0.008), and existence of node metastases (P = 0.029) and distant metastases (P = 0.036)." (PMID 27340318, 2016). "In conclusion, we demonstrate herein that sST2 can suppress tumour malignant growth locally and systemically by inhibiting IL-33-induced tumour angiogenesis and by modifying the tumour microenvironment." (PMID 27882929, 2016). "Again, the IL-33-educated macrophages significantly increased tumour cell invasion in this zebrafish model, indicating that IL-33-activated macrophages play a critical role in cancer metastasis." (PMID 27150562, 2016). "To relate our findings to pathophysiological relevance, we analysed IL-33 expression levels in various tumour tissues." (PMID 27150562, 2016). "The depletion of TAMs by clodronate markedly decreased the metastatic incidences in the lungs of IL-33 tumour-bearing mice, whereas the low metastatic rate in vector-tumour bearing mice remained unchanged." (PMID 27150562, 2016). "To provide further evidence of IL-33-induced metastasis, we developed an independent metastasis model in which luciferase-expressing primary tumours were implanted in the liver of each mouse." (PMID 27150562, 2016). "Mechanistically, ST2 protein was expressed in cancer cells and in CAFs, and IL-33 enhanced tumorigenesis through an increase of IL-6 expression in tumor tissue." (PMID 28119694, 2016). "Gain-of-function and loss-of-function experiments demonstrate that pericyte- and stromal cell-derived IL-33 is a crucial cytokine for recruitment of TAMs in the tumour microenvironment." (PMID 27150562, 2016). "To functionally link IL-33-primed TAMs with cancer invasion, we performed in vitro matrigel cancer invasion experiments in which tumour cells and macrophages were co-embedded in matrigel as spheroids." (PMID 27150562, 2016). "Supporting this result, immunohistochemical analysis of P29 tumours in both B6 and IL-33−/− mice demonstrated that scattered cells mostly had nuclear IL-33 staining, whereas some cells had both nuclear and cytoplasmic staining." (PMID 26775708, 2016). "In this study, the serum levels of IL-31 and IL-33 in EC patients were studied and assessed the interrelationship with clinical significance and some tumor markers." (PMID 27340318, 2016). "Corresponding results were obtained by overexpressing or downregulating IL1RL1 in NSCLC cells, thereby showing that the IL-33-driven tumor progression in this model relies on ST2." (PMID 28119694, 2016).
tumor (continued). "As presented above, IL-33 contributes to the modulation of the tumor environment by promoting the recruitment of pro-tumorigenic immune cells or the secretion of tumorigenic cytokines." (PMID 28119694, 2016). "Together, these results suggest that sST2 reduces IL-33-induced macrophage infiltration of the tumour stroma and M2a polarization of infiltrated macrophages." (PMID 27882929, 2016). "The IL-33 immunofluorescence was stronger, and the number of the IL-33+ cells per mm2 was larger in P29 tumours in B6 mice than those in IL-33−/− mice, but clear immunofluorescence signals was absent in A11 tumours." (PMID 26775708, 2016). "IL-33 stimulates ILC2s to secrete large amounts of IL-13, which has been shown to activate tumor-promoting MDSCs and their production of anti-inflammatory transforming growth factor-β (TGF-β)." (PMID 28536374, 2016). "Consistently, significant reduction of IL-33 expression in Panc02 tumours was detected in Il33−/− mice, supporting the fact that host cellular components are main sources of IL-33 production." (PMID 27150562, 2016). "Although these findings are primarily focused on the effect of IL-33 on primary tumour growth, our data show that IL-33 promotes metastasis through a distinct mechanism by which metastasis occurs through a primary tumour size-independent mechanism." (PMID 27150562, 2016). "IL-33 expression negatively correlated with the size of tumor necrosis at day 36 after tumor challenge in WT mice (r = −0.574; p = 0.007)." (PMID 26919112, 2016). "Approximately 50% of IL-33 tumour-bearing mice possessed visible pulmonary metastatic nodules on the surface of their lungs at week 6 after removal of primary tumours." (PMID 27150562, 2016). "Though, another study reported that IL-33 produced by PDGF-B-stimulated PC promoted metastasis through recruitment of tumor-associated macrophages in several human and mouse graft tumor models." (PMID 27867386, 2016). "We therefore consider that intratumoural IL-1β and IL-33 is primarily responsible for IL-33 expression in P29 tumours." (PMID 26775708, 2016). "We further investigated subpopulations of TAMs using M2 markers by FACS analysis in vector- and IL-33- overexpressed tumours." (PMID 27150562, 2016). "Patients with low tumour IL-33 expression had a median time to recurrence of 56.7 months, compared to 97 months for patients with higher tumour IL-33 expression." (PMID 27619158, 2016). "We have also reported that IL-33 promotes 3LL lung cancer progression by selecting for more ST2L-negative metastatic cells in the tumour microenvironment." (PMID 27882929, 2016). "In order to investigate the role of IL-33/IL-33R axis in tumor necrosis we used 4T1 metastatic breast cancer model in IL-33R-deficient BALB/c mice." (PMID 26919112, 2016). "In addition, loss of IL33 expression may also promote tumor escape in patients with metastatic prostate carcinomas or kidney renal clear cell carcinomas, via down-modulation of genes involved in antigen processing and of major histocompatibility complex (MHC-I/HLA)-genes." (PMID 28119694, 2016). "Another logistic analysis of multitarget diagnostic value evaluation verified that the sensitivity and specificity combination of IL-31 and IL-33 were also higher than the counterparts of tumor markers." (PMID 27340318, 2016). "A recent study reported that IL-33 in tumor microenvironment reduced the apoptosis and maintained the survival of MDSCs through induction of autocrine secretion of GM-CSF." (PMID 27517629, 2016). "Despite a high level of IL-33 expression, IL-33-overexpressing tumours grew at similar rates in vitro and in vivo as vector-transfected control tumours." (PMID 27150562, 2016). "Animals with TC1 (primary tumours) and A9+IL-33 tumours better maintained or gained weight throughout the study." (PMID 27619158, 2016).
tumor (continued). "IL-33 was also reported to reduce the accumulation of MDSCs in the spleen and tumor microenvironment, and to decrease the immunosuppressive activity of these cells, which limited tumor growth." (PMID 28119694, 2016). "Complementation of IL-33 expression in metastatic tumours upregulates APM expression and functionality of major histocompatibility complex (MHC)-molecules, resulting in reduced tumour growth rates and a lower frequency of circulating tumour cells." (PMID 27619158, 2016). "Here, we show that enhanced tumor necrosis in IL-33R−/− mice correlates to lower expression of angiogenic factors IL-33 and VEGF and is associated with slower tumor growth." (PMID 26919112, 2016). "IL-33 was abundantly present in the tumours established by the low-metastatic cells compared with those formed by the high-metastatic cells." (PMID 26775708, 2016). "This correlated with a reduction of macrophage recruitment to the tumor tissue, likely due to diminished CCL2 production by tumor cells with abrogated IL-33/ST2 signaling." (PMID 28119694, 2016). "We performed in vivo gain-of-function experiments that allowed studying the effect of IL-33 on tumour growth, TAM recruitment and tumour invasion and metastasis." (PMID 27150562, 2016). "Transgenic expression of IL-33 in mouse tumor models enhances cytotoxic activity of CD8+ T cells and NK cells." (PMID 26272855, 2015). "When injected into mice, the IL-33-producing tumor grew less, and the tumor infiltrating lymphocytes (TILs) were more abundant than in mice injected with control tumor cells." (PMID 26082774, 2015). "In this report, the investigators engineered two tumor cell lines to over-express (and secrete) IL-33." (PMID 26082774, 2015). "We detected the expression of IL-33 in tumor tissue, and IL-33 and its related cytokines in serum from BC patients." (PMID 24778632, 2014). "Since is released from tumor cells and necrotic cells in the context of intracellular cytokines, IL-33 can be seen as a novel of alarmin." (PMID 24312098, 2013). "Nuclear IL-33 expression was previously found in endothelial and epithelial cells in normal, chronically inflamed, and tumor tissues, pancreatic stellate cells, keratinocytes, and astrocytes." (PMID 23567618, 2013). "Although early reports document the expression of ST2 on leukaemic cell lines and on T cell lymphomas of patients, very few studies have addressed the role of IL-33/ST2 signaling on anti-tumor immune responses, tumor growth and/or metastasis." (PMID 21871091, 2011). "For that purpose, we double-stained human multi-tumor tissue microarrays with antibodies against IL-33 and CD31 or vWF." (PMID 18836528, 2008). "In the TME, epithelial, endothelial, fibroblast-like and tumor cells can all be a source of IL-33." (PMID 40317004, 2025). "However, in the tumour microenvironment, IL-33 can facilitate either pro-tumorigenic or anti-tumour responses, depending on the broader immune landscape." (PMID 41284319, 2025). "Indeed, our data indicated that BM-derived leukemic Treg cells respond to IL-33 upon tumor growth through increased expression of ST2 and that signaling has a crucial role in their augmented cytolytic function." (PMID 40691440, 2025). "Furthermore, IL‐33+ endothelial cells can increase vascular nourishment in tumors and increase the degree of tumor malignancy." (PMID 40860436, 2025). "Similarly, IL33 impaired the killing ability of HDNs against tumor cells, an effect that was rescued by DGAT1/2 inhibition; CSF2 did not impair the killing ability of HDNs against tumor cells." (PMID 41214328, 2025). "Another notable aspect of our study was the use of a reliable preclinical organoid model of EGC combined with scRNA‐seq data and the finding that IL‐33+ endothelial cells can promote angiogenesis and tumor proliferation in EGC by influencing adhesion molecules (PECAM1, CD34, and KRT17)." (PMID 40860436, 2025).
tumor (continued). "Recently, abnormal expression of IL-33 has been noted in the progression of numerous cancers, and the related signaling pathway has become a convergence point for many oncogenic signals, playing a pivotal role in tumor development and progression." (PMID 41272907, 2025). "Furthermore, antifungal treatment not only reduced IL33 expression but also resulted in tumor regression, highlighting a novel interplay between fungal mycobiota and immune pathways in PDAC progression." (PMID 40243755, 2025). "In the case of IL-33, its expression tends to be elevated during the early stages of tumor development but decreases in more advanced and poorly differentiated tumors, indicating a possible dual role—initially protective, followed by a shift toward tumor promotion in later stages." (PMID 40725273, 2025). "In addition, new evidence suggests that IL-33 is able to influence tumor development via eosinophil activation." (PMID 40149674, 2025). "IL-33 promotes tumor growth and increases the infiltration of ST2+ Treg cells." (PMID 39925809, 2025). "We aimed to assess whether the combination with DAC could increase the anti-tumor efficacy of IL-33." (PMID 40317004, 2025). "Furthermore, a separate study has suggested that the inhibition of TNF-α expression can lead to an upregulation of IL-33 in tumor cells, which in turn enhances the activity of DCs and cytotoxic T cells, thereby promoting anti-tumor immunity." (PMID 40948749, 2025). "Increased IL-33 in serum or tumor tissue may correlate with poor prognosis in several types of cancers, while, on the contrary, IL-33 can also stimulate anti-tumor immune response and thus contributes to tumor cell elimination." (PMID 40943444, 2025). "Conversely, some studies have indicated that IL-33 may stimulate anti-tumor immunity and limit sporadic CRC progression by enhancing interferon-γ responses." (PMID 40725273, 2025). "Moreover, IL-33 has been shown to have a significant effect on tumor growth and progression by enhancing angiogenesis in distinct types of cancer." (PMID 40520454, 2025). "In tumors, IL33 has also been found to be involved in the tumor’s pro-oncogenic and anti-oncogenic functions, with its main effects focused on the immune microenvironment, immune occurrence, and tumor-related inflammation." (PMID 39911848, 2025). "Given the complex regulation of gene expression, several key upregulated genes were found, including GATA4, SALL3, IL33, SOX10, and SCG3/SHC4, while the downregulation of keratin genes suggests a loss of epithelial differentiation, contributing to aggressive tumor behavior." (PMID 40647405, 2025). "In addition to Th2 cells, IL-33 can activate regulatory T cells and myeloid-derived suppressor cells to promote tumor growth and evade immune surveillance." (PMID 40647388, 2025). "Strikingly, the tumor-specific deletion of IL33 resulted in significant tumor regression." (PMID 40243755, 2025). "Moreover, tumor growth of Panc02‐sh#5 cells was comparable to that of Panc02‐shCont cells in IL‐33 KO mice." (PMID 40751595, 2025). "Next, we evaluated whether the combination with DAC could increase the anti-tumor efficacy of IL-33 in vivo." (PMID 40317004, 2025). "Moreover, tumor over-expression or exogenous administration of IL-33 can improve the therapeutic response to ICB in tumor-bearing mice." (PMID 40317004, 2025). "The multiple regression model investigating predictors of the IL-17A concentration, incorporating IL-8, IL-33, and tumor grade (degree of differentiation), revealed a statistically significant and robust relationship (p < 0.001), with the model explaining 70.66% of the variance in IL-17A levels." (PMID 40725273, 2025). "To exclude the direct effect of IL33 on tumor cells, we treated tumor cells with recombinant IL33." (PMID 41214328, 2025).
tumor (continued). "Overall, these studies not only unveil the critical role of eosinophils during ICI-mediated immune response and therapeutic success but also highlight the importance of activating stimuli, such as IFN-γ and IL-33, for tumor recruitment and induced anti-tumor responses of eosinophils." (PMID 40050933, 2025). "Previous studies have found that the IL-33/ST2 axis has tumor-promoting effects in cancer cells." (PMID 40216748, 2025). "Moreover, consistent with our in vitro data, fluorescent immunohistochemistry (IF-IHC) and immunohistochemistry (IHC) staining revealed that cisplatin treatment significantly increased IL-33 release in tumor tissues." (PMID 40216748, 2025). "However, TA99 CAR-T cells expressing both Super2 and IL-33 (Super2 + IL-33) was shown to have enduring effectiveness in delaying medium-sized tumor growth (∼7.5 mm × 6 mm) when administered on day 11 after inoculation." (PMID 41584600, 2025). "The mycobiome spurred the discharge of IL-33, which then propelled tumor growth." (PMID 39854185, 2025). "To explore whether DAC positively modulates the IL-33/ST2 axis in the tumor microenvironment, we assessed IL33 and ST2 expression in the TME of mice early after exposure to this epigenetic modifier drug (i.e., 3 days)." (PMID 40317004, 2025). "IL-33 not only regulates tumor growth but also helps to prevent metastatization." (PMID 40305195, 2025). "Furthermore, tumor-cell expression of IL-33 was necessary and sufficient for eosinophil-mediated anti-tumor responses and this mechanism contributed to the efficacy of ICI therapy." (PMID 40050933, 2025). "Exposure to DNA-damaging agents leads to increased IL-33 expression in tumor cells." (PMID 40216748, 2025). "Notably, lower IL-33 expression correlated with higher Gleason scores and lymphatic metastasis, highlighting its anti-tumour role." (PMID 40607441, 2025). "Inhibition of IL-33/ST2 may reduce NF-κB mediated transcriptional upregulation of PD-L1 in tumour and stromal cells, thereby enhancing response to PD-1/PD-L1 blockade." (PMID 41284319, 2025). "In this scenario, we hypothesized that tumor-derived IL-33 could participate in the strong activation of BMMCs." (PMID 40372523, 2025). "In contrast, IL-17A and IL-33 levels decreased progressively with declining tumor differentiation, which may indicate their involvement in early stage inflammatory signaling and the subsequent suppression of immune responses in more advanced cancer." (PMID 40725273, 2025). "Their pro-tumor activities can be curtailed by targeting cytokine signals (like IL-25) or reprogramming their inhibitory checkpoints (like PD-1), while their anti-tumor capacities can be harnessed by combining IL-33-based activation with checkpoint inhibitors." (PMID 40963622, 2025). "Furthermore, IL-33 contributes to the induction of Th9 cells, a subset of Th cells that produce IL-9 and have potent anti-tumor effects." (PMID 41163402, 2025). "This hypothesis was further confirmed by the upregulation of the surface expression of CD107a and by the release of TNFα by MCs incubated with tumoral organoids, an effect dependent on IL-33 released by tumor organoids." (PMID 41368640, 2025). "Similarly to what was observed in our xenograft models, in both the CT-2A and GL261 immunocompetent models, IL-33 expression is located mostly outside the tumor bulk." (PMID 39931535, 2025). "In IL33−/− and IL1rl1−/− mice, tumor growth was faster than in the control." (PMID 40305195, 2025). "Importantly, a multivariate model including IL-8, IL-17A, IL-33, and tumor grade accounted for over 70% of the variance in IL-17A expression, reinforcing the complex interplay among these cytokines in shaping the tumor microenvironment." (PMID 40725273, 2025).